RBM6 (RNA binding motif protein 6)
Description:
Specifically binds poly(G) RNA homopolymers in vitro.
Synonyms: DEF3; DEF-3; 3G2; NY-LU-12; g16; HLC-11
Tractability: PROTAC: UniProt records ubiquitination sites on it; ubiquitination databases record sites on it; its protein half-life has been measured.
Gene: Protein-coding gene on chromosome 3 (49,940,007 to 50,100,045, forward strand). Ensembl gene ENSG00000004534.
Subcellular location: Nucleus
Subcellular location (Human Protein Atlas): Nuclear speckles; Cytoplasmic bodies
Gene Ontology:
Molecular function: protein binding; RNA binding; DNA binding; nucleic acid binding
Biological process: RNA processing
Cellular component: nucleus
Genetic constraint (gnomAD): Loss-of-function variants: 19 observed, 130.64 expected, observed/expected ratio (o/e) 0.15, 90% interval 0.1 to 0.21. The upper end of that interval is the gene's LOEUF score, 0.21, which puts it in group 1 of 6, group 1 being the genes least tolerant of losing a copy. Missense variants: 1,097 observed, 1,403.2 expected, observed/expected ratio (o/e) 0.78, 90% interval 0.74 to 0.82. Synonymous variants: 428 observed, 488.13 expected, observed/expected ratio (o/e) 0.88, 90% interval 0.81 to 0.95.
Homologues: Orthologues: macaque RBM6 (98% identical), dog RBM6 (92% identical), rabbit RBM6 (92% identical), pig RBM6 (91% identical), guinea pig RBM6 (90% identical), mouse Rbm6 (89% identical), rat Rbm6 (88% identical), chimpanzee RBM6 (88% identical), zebrafish rbm6 (25% identical), Drosophila melanogaster CG4887 (16% identical), Drosophila melanogaster CG4896 (15% identical), Caenorhabditis elegans rbm-5 (14% identical). Paralogues in human: RBM5 (22% identical), RBM10 (22% identical).
Diseases named in the same sentence as RBM6 in open-access papers:
RBM6 is named in the same sentence as 37 diseases in open-access papers, as found by Europe PMC text mining. Sharing a sentence is not in itself a finding about the gene and the disease. The quoted sentences say what the papers report.
lung carcinoma (7 papers, 2007 to 2025). "Specifically, RBM6 mutations have been found in 1.5% of breast (n = 1084 cases) and 3.1% of lung cancers (n = 487 cases)." (PMID 34718714, 2021). "RNA‐binding motif protein 6 (RBM6), as a member of the RBM family, has been reported to be associated with a variety of tumours, for example, RBM6 inhibits laryngocarcinoma but promotes lung cancer, however its relationship with prostate tumours has been unclear." (PMID 39900560, 2025). "Interestingly, in addition to breast and lung cancer, RBM6 is mutated in 8.8% of uterine and in 7.2% of stomach cancer." (PMID 34718714, 2021). "Moreover, mutations in RBM6 were associated with the loss of heterozygosity in the majority of lung cancer patients." (PMID 33287695, 2020). "(ii) RBM6 is mapped to 3p21.3 region, which is frequently deleted in heavy smoker lung cancer and other tissues carcinomas." (PMID 34718714, 2021). "For example, as regulators of alternative splicing of apoptotic genes, RBM5, RBM6 and RBM10 are frequently deleted or mutated in lung cancer." (PMID 34398362, 2021). "While the RBM6 gene has been shown to be either deleted or disrupted in some lung cancers, RBM6 mRNA was recently found to be significantly upregulated in breast cancer." (PMID 17908320, 2007). "SFs, including QKI, RBM4, RBM5, RBM6, RBM10, and SRSF1, were involved in the development of lung cancer, as SFs play a regulatory role in splicing." (PMID 33047900, 2020).
breast carcinoma (5 papers, 2007 to 2024). "A recent quantitative proteome of 375 cancer cell lines revealed low levels of RBM6 protein in breast cancer cell lines when compared to other types of cancer." (PMID 34718714, 2021). "Toward this end, we took advantage of MCF7 breast cancer cell line, which is known to lack RBM6 expression." (PMID 34718714, 2021). "Remarkably, similar correlation between RBM6 and Fe65 expression was also observed in 10,953 cancer patients including breast cancer patients." (PMID 34718714, 2021). "Moreover, we observed that RBM6 protein levels are downregulated in metastatic breast cancer cell lines when compared primary breast cancer cell lines." (PMID 34718714, 2021). "Furthermore, we observe that RBM6 protein is significantly lost in metastatic breast tumors compared with primary tumors, thus suggesting RBM6 as a potential therapeutic target of advanced breast cancer." (PMID 34718714, 2021). "We found that RBM6 is drastically downregulated in metastatic carcinoma when compared to invasive carcinoma and hyperplasia, irrespective of breast cancer subtype." (PMID 34718714, 2021). "RBM6 mRNA was reported to be highly upregulated in many cancer types, such as breast cancer, malignant fibrous histiocytoma, ovary cystadenoma, non-Hodgkin’s lymphoma, and pancreatic cancer." (PMID 33584809, 2020).
breast tumors (2 papers, 2007 to 2021). "In breast tumour tissue, chimeric expression was associated with elevated levels of RBM6 and RBM5 mRNA, and increased tumour size." (PMID 17908320, 2007). "Notably, RBM6 immunohistochemical staining of human tissue microarrays (TMA) shows that RBM6 protein level is significantly lost in human metastatic breast tumors when compared to primary tumors." (PMID 34718714, 2021). "We previously reported that RBM6 mRNA expression was significantly upregulated in human breast tumour tissue compared to non-tumour tissue." (PMID 17908320, 2007).
prostate carcinoma (2 papers, 2025). A carcinoma that arises from epithelial cells of the prostate gland. "To gain a deeper understanding of the relationship between RBM6 and prostate cancer, we analysed the TCGA database." (PMID 39900560, 2025). "Our findings revealed that RBM6 expression is elevated in tumours, indicating at its potential role as a cancer‐promoting factor in prostate cancer." (PMID 39900560, 2025). "To further investigate how RBM6 impacts the prognosis of prostate cancer patients, we analysed the GEO database (GSE196600) and discovered a close correlation between RBM6 and changes in cell migration ability." (PMID 39900560, 2025). "Our results demonstrated that RBM6 was highly expressed in the RM1, PC‐3 and DU145 prostate cancer cell lines." (PMID 39900560, 2025).
acute myeloid leukemia (1 paper, 2024). Acute myeloid leukemia (AML) is a group of neoplasms arising from precursor cells committed to the myeloid cell-line differentiation. "Additionally, in the context of acute myeloid leukemia (AML), particularly the megakaryoblastic subtype, an in vitro study identified a genetic mutation leading to a RBM6-CSF-1R fusion." (PMID 39457693, 2024).
adenocarcinoma of the lung (1 paper, 2007). "In addition, the RBM6 protein was first isolated in an autologous antibody screen from a patient with adenocarcinoma of the lung, demonstrating an association between elevated levels of RBM6 protein and cancer." (PMID 17908320, 2007).
asthma (1 paper, 2024). "In addition, our MAGMA analyses implicated another four pleiotropic genes—RERG, RBM6, SDK1, and HLA-B as potential targets for further investigation into asthma and GERD." (PMID 39223263, 2024). "After comparison, asthma and GERD were found to share six genes (ERBB3, RBM6, HLA-B, SDK1, RERG, RAB5B), one of which, ERBB3, was also significantly associated with both eczema and GERD." (PMID 39223263, 2024).
COVID-19 (1 paper, 2024). A disease caused by infection with severe acute respiratory syndrome coronavirus 2. "The identification of MYBL2, RBM6, VEPH1, AHNAK2, GNG10, and DUSP14 as key genes offers valuable insights into the molecular mechanisms underpinning glioma progression and its interaction with COVID-19." (PMID 39684661, 2024).
glioma (1 paper, 2024). A benign or malignant brain and spinal cord tumor that arises from glial cells (astrocytes, oligodendrocytes, ependymal cells). "RBM6 and VEPH1 presented higher expression in primary gliomas, with RBM6 p = 2.0 × 10−9 and VEPH1 p = 8.2 × 10−5, indicating a significant potential protective role." (PMID 39684661, 2024).
invasive breast carcinoma (1 paper, 2021). A carcinoma that infiltrates the breast parenchyma. "Concordantly, we demonstrated that RBM6 level is downregulated in invasive breast cancer." (PMID 34718714, 2021).
invasive carcinoma (1 paper, 2021). A carcinoma that is not confined to the epithelium, and has spread to the surrounding stroma. "To further corroborate this, we performed immunohistochemical staining of RBM6 in human tissue microarrays (TMA) containing hyperplasia, invasive carcinoma of no special type and metastatic breast carcinoma." (PMID 34718714, 2021).
laryngeal carcinoma (1 paper, 2023). Carcinoma that arises from the laryngeal epithelium. "Furthermore, RBM6 is downregulated in laryngeal carcinoma tissues and cell lines, whose upregulation can inhibit cell proliferation and promote apoptosis by activating the ERK pathway." (PMID 36734243, 2023).
pancreatic cancer (1 paper, 2020). "proved that upregulated RBM6 in pancreatic cancer may be released into the blood, which could be a candidate and potential serum biomarker for early diagnosis of pancreatic cancer." (PMID 33584809, 2020).
prostate tumours (1 paper, 2025). "RBM6, implicated in the progression of multiple tumour types but unexplored in prostate tumours, was found to indicate potential therapeutic implications due to its elevated expression in prostate tumours." (PMID 39900560, 2025). "By utilising the HPA database, we analysed the expression levels of RBM6 in prostate tumours and corroborated these findings through WB analysis." (PMID 39900560, 2025). "Collectively, these findings strongly suggest that the knockdown of RBM6 can effectively inhibit the migration of prostate tumour cells." (PMID 39900560, 2025). "This study found that RBM6 can promote the migration ability of prostate tumours through CDH1, and its expression is regulated by ZEB1 transcription." (PMID 39900560, 2025). "This indicates the promising potential of RBM6 as both a predictive biomarker and a therapeutic target in prostate tumours." (PMID 39900560, 2025). "These experiments confirmed that the expression level of RBM6 in prostate tumours is significantly higher compared to adjacent non‐tumour tissues." (PMID 39900560, 2025). "Our findings reveal that RBM6 promotes the migratory capacity of prostate tumours by inhibiting CDH1, and its activity is also regulated by the key transcription factor ZEB1 of the EMT pathway." (PMID 39900560, 2025). "Thus, under normal conditions, RBM6 promotes prostate tumour cell migration, but in the context of high ZEB1 expression, it inhibits migration." (PMID 39900560, 2025). "Furthermore, our findings indicate that RBM6 has the capacity to enhance the migratory abilities of prostate tumour cells." (PMID 39900560, 2025). "Interestingly, RBM6 inhibited prostate tumour migration when ZEB1 was highly expressed, and increased RBM6 inhibited tumour migration in enzalutamide‐resistant LNCaP cell lines." (PMID 39900560, 2025). "Therefore, we hypothesized that the promotion effect of RBM6 on the migration ability of prostate tumours may be played by CDH1." (PMID 39900560, 2025). "In this study, we observed that RBM6 is abundantly expressed in prostate tumours and exhibits a negative correlation with patient prognosis." (PMID 39900560, 2025).
skin cancer (1 paper, 2025). "Six genes (RBM6, DNAJC18, SPIRE2, CPNE1, SEPT2, and ERAP2) presented causal associations with skin cancer." (PMID 41209561, 2025).
cancer (17 papers, 2007 to 2025). A tumor composed of atypical neoplastic, often pleomorphic cells that invade other tissues. "Altogether, our findings provide the basis for using cisplatin as a promising new therapy of RBM6-deficient cancer cells." (PMID 34718714, 2021). "Accordingly, RBM6-deficient cancer cells are vulnerable to ATM and PARP inhibition and show remarkable sensitivity to cisplatin." (PMID 34718714, 2021). "Herein, we describe a previously unrecognized role of RBM6 in regulating genomic integrity and DNA repair that can be associated with cancer progression." (PMID 34718714, 2021). "The sensitivity to PARPi was also evident in RBM6-deficient HeLa cells, suggesting that the ‘BRCAness’ phenotype of RBM6-deficient cells displays synthetic lethal interaction with PARPi in a broader range of cancer cells." (PMID 34718714, 2021). "(iii) RBM6 is mutated in 2.4% of diverse human cancers from multiple origins (n = 10967 cases)." (PMID 34718714, 2021). "The dysregulation of RBM6 gene expression might be associated with cancer development." (PMID 39684661, 2024). "Other RBM proteins family members also participate in suppressing proliferation in different cancers, such as RBM6, RBMS1, RBMS2, RBMS3, etc.." (PMID 34804951, 2021). "In line with this, RBM6 depletion renders cancer cells vulnerable to ATM and PARP inhibition and exhibits pronounced sensitivity to cisplatin." (PMID 34718714, 2021). "Gene set enrichment analysis revealed several pathways that were altered following RBM6 depletion including HR and cancer-related pathways." (PMID 34718714, 2021). "It was shown that some members of the RBM proteins family play a tumor-suppressive role in cancers, inhibiting tumorigenesis and cell proliferation, promoting tumor cell apoptosis, and limiting cell migration and invasion, such as RBM6 and RBM38." (PMID 34804951, 2021). "The RNA-binding motif protein 6, RBM6, is a known alternative splicing factor that harbors tumor suppressor activity and is frequently mutated in human cancer." (PMID 34718714, 2021). "In support of this, RNA-seq expression data of 1375 cancer cell lines from diverse origins show a mild, but statistically significant, correlation between RBM6 and Fe65 expression." (PMID 34718714, 2021). "Research suggests that RBM6 exerts a tumor-suppressive role across multiple cancer types." (PMID 39697342, 2024). "RBM5, RBM6, and RBM10 are commonly deleted, mutated, and/or under-expressed or overexpressed genes in many cancers; however, they have different roles in in vitro colony formation assays, partially due to their antagonistic regulation of NUMB alternative splicing." (PMID 36006412, 2022). "(iv) Insertional mutagenesis experiments support RBM6 as a cancer driver gene." (PMID 34718714, 2021). "Furthermore, RBM6 was reported to inhibit invasion and induce apoptosis, consequently suppressing the cancer cell growth and progression in laryngocarcinoma." (PMID 32947864, 2020). "Together, these lines of evidence suggest that both RBM5 and RBM6 might play a tumor suppressive role in different types of cancers." (PMID 32947864, 2020). "Conversely, certain SFs, including QKI, RBM5, RBM6, and RBM10, act as tumor suppressors and exhibit anti-cancer characteristics." (PMID 39004679, 2024). "Of the eight modeling RBPs, half were upregulated including PABPC1, PRPF6, OAS1, IPO7, and half were downregulated including RBM5, RBM6, LSM12, and FXR7 in cancer cases." (PMID 33584809, 2020).
tumor (15 papers, 2007 to 2025). "The loss or mutation of RBM6 can lead to aberrant splicing of certain tumor-associated genes, thereby facilitating tumorigenesis and progression." (PMID 39697342, 2024). "One interpretation of the observation of a positive correlation between RBM6-RBM5 chimeric expression and RBM6 expression is that chimeric expression represents a small fraction of tumour-associated aberrant "run-off" or "leakage" RBM6 transcription events." (PMID 17908320, 2007). "The molecular mechanism underlying the tumor suppressor activity of RBM6 remains elusive." (PMID 34718714, 2021). "Interestingly, we observed that RBM6-deficient tumors tend to be larger than control tumors supporting its role as a tumor suppressor." (PMID 34718714, 2021). "The importance of RBM6 tumour-associated expression regulation remains to be determined." (PMID 17908320, 2007). "The RNA-binding motif protein 6 (RBM6) is also known as 3g2, G16, def3, def-3, hlc-11, and nylu-12 and is located in the 3p21.3 tumor suppressor region in humans." (PMID 33718153, 2021). "All these results indicate that RBM6 is a tumor suppressor; however, research on RBM6 is still very limited, and more is needed in the future to fully characterize RBM6 function in disease systems." (PMID 33718153, 2021). "RBM5 (RNA-binding motif protein 5) and RBM6 (RNA-binding motif protein 6) were initially reported as tumor suppressors." (PMID 33584809, 2020). "Altogether, these studies highly suggest that RBM10, similar to RBM5 and RBM6, possesses a tumor suppressive function via different mechanisms." (PMID 32947864, 2020). "Here we report that RBM6 mRNA expression was also elevated in skeletal muscle tumour tissue compared to normal, from ~1.5-fold in one tumour to ~14-fold in a different tumour." (PMID 17908320, 2007). "RBM6 has previously been reported to play an important role in a variety of tumours." (PMID 39900560, 2025). "Previous works suggested that RBM6 exhibits tumor suppressor activity." (PMID 34718714, 2021). "Since many tumor suppressor genes play a role in DNA repair, and since RBM6 is phosphorylated in response to DNA damage including IR, we were prompted to investigate whether RBM6 is involved in DSB repair." (PMID 34718714, 2021). "Regarding CNAs present in 419 tumour suppressor genes, losses of the most common CNA tumour suppressor genes are found at 3p21.31 specified by genes RBM6 in 35 HRO-, RBM5 in 30 HRO-, LIMD1 in 28 HRO-, TCTA in 26 HRO- and at 3p22.2 by MLH1 in 33 HRO-tumours." (PMID 28486536, 2017). "Losses of RBM6 (23/26 G1; 10/20 G3), MLH1 (22/26 G1; 9/20 G3) and LIMD1 (21/26G1; 5/20 G3) on 3p are predominantly present in Fuhrman G1 HRO tumours." (PMID 28486536, 2017). "Transcription-induced chimeras of the neighboring genes RBM6 and RBM5 were identified in human tumour tissues." (PMID 17908320, 2007). "We propose that RBM6 role in DSB repair may contribute, at least in part, to its tumor suppressor function." (PMID 34718714, 2021). "RBM6 was highly expressed in the chimeric positive skeletal muscle tumour compared to the chimeric negative skeletal muscle tumour." (PMID 17908320, 2007).
RBM6 also shares sentences with these, for which no sentence is quoted: acute megakaryoblastic leukemia (1 paper); Autoimmunity (1); bladder cancer (1); duodenitis (1); eczema (1); Fanconi anemia (1); gastritis (1); malignant fibrous histiocytoma (1); metabolic disorders (1); metastatic carcinoma (1); neurological diseases (1); non-Hodgkin lymphoma (1); Obesity (1); ovary cystadenoma (1); prostate adenocarcinoma (1); schizophrenia (1); small cell lung carcinoma (1); stomach cancer (1); theileriasis (1); type 2 diabetes (1).